STAMBPL1 (STAM binding protein like 1)
Diseases named in the same sentence as STAMBPL1 in open-access papers:
STAMBPL1 is named in the same sentence as 22 diseases in open-access papers, as found by Europe PMC text mining. Sharing a sentence is not in itself a finding about the gene and the disease. The quoted sentences say what the papers report.
prostate carcinoma (6 papers, 2019 to 2025). A carcinoma that arises from epithelial cells of the prostate gland. "This is consistent with recent studies that found high amounts of STAMBPL1 protein in prostate cancer PC3 (derived from bone metastasis) and DU145 cell lines (derived from brain metastasis)." (PMID 32636467, 2020). "STAMBPL1 depletion was found to induce apoptosis by promoting the degradation of the protein XIAP, suggesting that targeting STAMBPL1 might offer a promising therapeutic strategy for prostate cancer." (PMID 38419066, 2024). "In prostate cancer, STAMBPL1 did not affect the stability of Survivin protein, which might differ because of genetic alterations in this cancer cells." (PMID 35066747, 2022).
breast carcinoma (5 papers, 2020 to 2025). "In this study, we discovered that STAMBPL1 could upregulate the expression of the hypoxia-inducible factor HIF1α in breast cancer cells." (PMID 40208233, 2025). "Nonetheless, whether STAMBPL1 influences the prognosis of breast cancer patients is unclear and requires further research." (PMID 36685836, 2022). "Our previous research revealed that the deubiquitinase STAMBPL1 enhances the stability of MKP-1, thereby promoting cisplatin resistance in breast cancer." (PMID 40208233, 2025). "Depleting STAMBPL1 and MKP-1 can enhance the sensitivity of breast cancer cells to cisplatin by increasing JNK phosphorylation and activation." (PMID 36765039, 2023). "Moreover, STAMBPL1 could regulate snail stability by deubiquitination mechanisms in breast cancer." (PMID 36685836, 2022). "We identify a previously undiscovered biological function of STAM-binding protein like 1 (STAMBPL1) deubiquitinase in the EMT process in lung and breast carcinomas." (PMID 32636467, 2020). "To experimentally investigate the potential role of STAMBPL1 in the EMT process, we used the lung adenocarcinoma (A549, NCI-H838) and breast carcinoma (MCF7, SUM159) cell lines, displaying either epithelial or mesenchymal traits, respectively." (PMID 32636467, 2020).
gastric cancer (4 papers, 2018 to 2024). A primary or metastatic malignant neoplasm involving the stomach. "STAMBPL1 has been implicated in diverse cancer types, notably colorectal cancer, as reported in the literature, gastric cancer and lung cancer." (PMID 38419066, 2024). "Interestingly, like N14-77 polyps, stomach cancers that harbor STAMBPL1 F407fs or K405fs mutation also display upregulation of MYC target genes and downregulation of trafficking genes." (PMID 30018743, 2018). "STAMBPL1 expression was found to be significantly upregulated in gastric cancer compared to adjacent tissue, and the expression levels increased with advanced stages." (PMID 38419066, 2024). "The ANKRD22 is reported to promote non-small cell lung cancer, and STAMBPL1 is oncogenic in gastric cancer." (PMID 34178034, 2021). "In addition, with increasing stages of gastric cancer (stage I-IV), STAMBPL1 protein expression was considerably upregulated, which could explain the emergence of apoptotic resistance in gastric carcinogenesis." (PMID 35066747, 2022). "Especially in gastric cancer cells, long non-coding RNA NEAT1 could regulate STAMBPL1 expression and promote its malignant behavior." (PMID 38419066, 2024).
renal carcinoma (4 papers, 2018 to 2025). A carcinoma arising from the epithelium of the renal parenchyma or the renal pelvis. "To assess the role of STAMBPL1 in the efficacy of immunotherapy in renal cancer, we constructed subcutaneous tumor‐bearing mice models using control Renca cells or STAMBPL1 KD Renca cells and those mice were administrated the anti‐PD‐1 antibody (αPD‐1)." (PMID 39527690, 2025). "It has been described that STAMBPL1 stabilises the anti-apoptotic regulator Survivin in renal cancer cells." (PMID 35066747, 2022). "It has been described that the anti-apoptotic protein Survivin, a member of the inhibitor of apoptosis protein (IAP) family is deubiquitinylated by STAMBPL1 in renal cancer cells." (PMID 35066747, 2022). "Taken together, our study suggests that CEP enhances TRAIL-induced apoptosis by degradation of survivin through downregulation of STAMBPL1 deubiquitin enzyme in renal carcinoma cells." (PMID 30360403, 2018). "Hence, the further investigation elucidating the mechanism by which STAMBPL1/AXL regulates resistance to sunitinib in renal cancer was needed in the future." (PMID 39527690, 2025). "STAMBPL1 was recently reported to regulate Survivin abundance in renal carcinoma." (PMID 35066747, 2022). "Targeting the STAMBPL1/AXL axis significantly enhances the efficacy of sunitinib treatment and immunotherapy, hence it is worth exploring whether STAMPBP1 expression is associated with the prognosis in patients with renal cancer." (PMID 39527690, 2025). "Lastly, when investigating the synergistic effects of STAMBPL1 inhibition with αPD‐1 or sunitinib in renal cancer, it is preferable to utilize small molecule inhibitors targeting STAMBPL1 rather than employing STAMBPL1 KD tumor cells." (PMID 39527690, 2025).
colon cancer (2 papers, 2021 to 2024). "STAMBPL1 knockout or correction of the heterozygous STAMBPL1 mutation in a human colon cancer cell could suppress xenograft tumor growth." (PMID 38419066, 2024). "However, subsequent analysis using Taqman qPCR showed that the STAMBPL1-FAS fusion isoform can be found in all 6 cancer samples, implying a wider distribution of this gene fusion in colon cancers." (PMID 33907296, 2021).
hepatocellular carcinoma (2 papers, 2024 to 2025). A malignant tumor that arises from hepatocytes. "The colony formation experiments additionally revealed that overexpressing STAMBPL1 heightened the proliferative capacity of hepatocellular carcinoma cells." (PMID 38419066, 2024). "Subsequent observations revealed that the reduction of STAMBPL1 in hepatocellular carcinoma cell lines led to the inhibition of cell proliferation, invasion, and metastasis." (PMID 38419066, 2024). "In addition, the results from the colony formation experiment demonstrated that the downregulation of STAMBPL1 suppressed the proliferation of hepatocellular carcinoma cells." (PMID 38419066, 2024). "The Integrative Molecular Database of Hepatocellular Carcinoma database (HCCDB) database further confirmed the upregulation of STAMBPL1 in HCC tissues compared with paracancerous tissues." (PMID 38419066, 2024). "Analysis of tissue immunofluorescence unveiled a substantial correlation between STAMBPL1 expression and the presence of PCNA and Ki67 in both hepatocellular carcinoma (HCC) tissue and adjacent non-cancerous tissues." (PMID 38419066, 2024).
liver cancer (2 papers, 2024 to 2025). An epithelial or non-epithelial malignant neoplasm that arises from the liver. "The study employed molecular docking techniques to analyze the interaction between the STAMBPL1 protein and commonly used first-line drugs for clinical liver cancer (including sorafenib, regorafenib, lenvatinib, and cabozantinib)." (PMID 38419066, 2024).
lung carcinoma (2 papers, 2020). "Further, our combined prognosis showed that the combined high expression of SP5, FOXP1, ROBO1, DPP4, CDYL2, and STAMBPL1 is associated to patients’ better clinical prognosis of patients with lung cancer." (PMID 32552834, 2020). "To examine this, we conducted a Kaplan–Meier survival analysis of 492 patients with lung cancer expressing STAMBPL1." (PMID 32636467, 2020). "Importantly, STAMBPL1 is highly expressed in metastatic tissues compared to matched primary tumour of the same lung cancer patient and its expression predicts poor prognosis." (PMID 32636467, 2020).
colorectal cancer (1 paper, 2024). A primary or metastatic malignant neoplasm that affects the colon or rectum. "Recent studies indicate that STAMBPL1 plays a role in the advancement of various cancer types, such as gastric, breast, prostate, and colorectal cancers." (PMID 38419066, 2024).
metastasis (1 paper, 2021). The spread or migration of cancer cells from one part of the body (where they first appeared) to another. "STAMBPL1-FAS fusion isoform was identified in sample 1 M (metastasis cancer) and 2 M (the metastasis cancer): XM_011539985 from STAMBPL1 and XM_011539766.2 from FAS." (PMID 33907296, 2021).
renal cell carcinoma (1 paper, 2023). "Moreover, using the TCGA dataset, we observed a shorter overall survival in patients with renal cell carcinoma (RCC) showing high c-FLIP or STAMBPL1 expression levels." (PMID 37511599, 2023).
triple-negative breast carcinoma (1 paper, 2025). An invasive breast carcinoma which is negative for expression of estrogen receptor (ER), progesterone receptor (PR), and human epidermal growth factor receptor 2 (HER2). "We demonstrated that STAMBPL1 increased HIF1A transcription in a non-enzymatic manner, thereby activating the HIF1α/VEGFA signaling pathway to facilitate triple-negative breast cancer angiogenesis." (PMID 40208233, 2025).
cancer (10 papers, 2018 to 2025). A tumor composed of atypical neoplastic, often pleomorphic cells that invade other tissues. "Importantly, K405 and F407, which flank G406, are the most frequently mutated residues of STAMBPL1 in human cancers, with frameshift mutations recurrently found." (PMID 30018743, 2018). "Kyoto Encyclopedia of Genes and Genomes (KEGG) pathway enrichment analysis revealed that STAMBPL1 was involved in modulating transcriptional misregulation in cancer and NF‐kappa B signaling pathway." (PMID 39527690, 2025). "Mechanistically, we found that STAMBPL1 positively modulated mesenchymal and immune evasion phenotypes of cancer cells largely through removing ubiquitination on AXL, one member of TAM receptors." (PMID 39527690, 2025). "This study demonstrated that TBMS-1 sensitizes cancer cells to the apoptosis effect of TRAIL via STAMBPL1-dependent downregulation of c-FLIP." (PMID 37511599, 2023). "STAMBPL1 is a K63-specific DUB reported to have higher expression in cancer tissue than in adjacent control tissues." (PMID 37892185, 2023). "Taken together, our findings indicated that TBMS-1 downregulates c-FLIP by downregulating STAMBPL1 deubiquitinating enzymes in various cancer cells." (PMID 37511599, 2023). "STAMBPL1 expression is ubiquitous among a variety of human tissues and shows overexpression in human cancer." (PMID 35066747, 2022). "Consistently, SUM159 and NCI-H838 cancer cells became less migratory upon STAMBPL1 depletion as observed by transwell migration and wound scratch assays." (PMID 32636467, 2020). "To popularize phenomenon by honokiol treatment, we examined the alteration of STAMBPL1 by honokiol in other cancer cells." (PMID 31817770, 2019). "Collectively, we showed that honokiol sensitizes cancer cells to TRAIL-induced apoptosis through STAMBPL1-mediated survivin and c-FLIP downregulation." (PMID 31817770, 2019). "Accordingly, we hypothesized that STAMBPL1 could be involved in the regulation of cancer immunotherapy." (PMID 39527690, 2025). "Herein, our data provide novel insights into the pathophysiology of H. pylori infection and might be useful to develop therapeutic strategies targeting STAMBPL1 in cancer." (PMID 35066747, 2022). "This analysis showed higher STAMBPL1 expression in the metastatic lesion, along with more vimentin and reduced E-cadherin protein staining, further supporting a role of STAMBPL1 in an aggressive cancer phenotype." (PMID 32636467, 2020). "Honokiol induced STAMBPL1 downregulation in tested cancer cells (ACHN, A498, A549, and Hela cells)." (PMID 31817770, 2019). "Therefore, honokiol-induced STAMBPL1 downregulation is a critical role in sensitization cancer cells to TRAIL-mediated apoptosis via degradation of survivin and c-FLIP." (PMID 31817770, 2019). "STAMBPL1 has various molecular functions, such as functioning as a positive regulator of Tax-mediated NF-κB activation, but the role of STAMBPL1 is unclear in cancer cells." (PMID 30360403, 2018). "Collectively, targeting the STAMBPL1/TRIM21/AXL axis can decrease mesenchymal phenotype and potentiate anti‐tumor efficacy of cancer therapy." (PMID 39527690, 2025). "In order to enhance the reliability of our conclusion regarding the STAMBPL1 KD‐mediated destabilization of AXL, primary cancer cells were isolated from KIRC tissues." (PMID 39527690, 2025). "To further elucidate the impact of the STAMBPL1/TRIM21/AXL axis on metastasis in vivo, we constructed the tail‐vein cancer metastasis model using 786‐O sublines in BALB/c nude mice." (PMID 39527690, 2025). "STAM Binding Protein Like 1 (STAMBPL1), functions as a deubiquitinase (DUB) and plays a significant role in various types of cancers." (PMID 38419066, 2024). "Our results indicated that TBMS-1 degraded c-FLIP protein in a STAMBPL1-dependent manner, resulting in an increase in TRAIL-mediated apoptotic cancer cell death." (PMID 37511599, 2023).
cancer (continued). "Accordingly, genetic depletion and CRISPR-mediated gene knockout of STAMBPL1 leads to marked recovery of epithelial markers, SNAI1 destabilisation and impaired migratory capacity of cancer cells." (PMID 32636467, 2020). "We then probed the ability of STAMBPL1 to reprogramme and induce mesenchymal markers in MCF7 and A549 cancer cells that normally display epithelial traits." (PMID 32636467, 2020). "It was observed that STAMBPL1 KD markedly reduced the abundance of AXL without affecting AXL RNA levels in primary cancer cells." (PMID 39527690, 2025). "Due to the multi-dimensional landscape of cancer cells to undergo EMT, we explore during which EMT-promoting condition(s) STAMBPL1 may be involved in." (PMID 32636467, 2020). "Based on our combinatorial study comprising functional cancer genomics, human cancer specimens and biochemical approaches, we propose STAMBPL1 as a potential new predictive signature of EMT, and present a therapeutic opportunity of targeting STAMBPL1 to exhaust the EMT potential of cancer cells." (PMID 32636467, 2020). "Conclusively, by defining a role of STAMBPL1 in EMT and as a potential therapeutic target in multiple human carcinomas, we propose that targeting of STAMBPL1 may provide an alternative approach for treatment of cancer progression by exhausting the EMT potential of cancer cells." (PMID 32636467, 2020).
tumor (10 papers, 2020 to 2025). "Further, as EMT is strongly implicated in greater invasive abilities of tumour cells, it predicts that silencing of STAMBPL1 should cause suppressive effects on cell migration." (PMID 32636467, 2020). "Further studies to explore the interaction between the additional targets and the STAMBPL1/TRIM21/AXL axis will expand the understanding of the function of STAMBPL1 in tumor progression." (PMID 39527690, 2025). "The TIMER online tumor Cancer research database and TCGA database indicated that STAMBPL1 is generally highly expressed in a majority of tumor types including HCC." (PMID 38419066, 2024). "Through the analysis of TCGA expression symbol and clinicopathological information, it was found that the expression of STAMBPL1 increased with the variation of tumor stage and grade in HCC." (PMID 38419066, 2024). "The single cell sequencing data and the Spatial transcriptome data showed that the high STAMBPL1 expression is mainly located in tumor cells." (PMID 38419066, 2024). "The results indicated a substantial reduction in tumor growth rate and volume in nude mice upon downregulation of STAMBPL1." (PMID 38419066, 2024). "Several deubiquitination enzymes, such as CSN5, USP1, USP19, and STAMBPL1, prevent the ubiquitin degradation process of survivin and stabilize its expression, leading to tumor progression and therapeutic resistance 48-50." (PMID 38356707, 2024). "Using TOST we identified two equivalently changed genes (SPICE1 and MCEMP1) and one inverse changed gene (STAMBPL1) by comparing tumor tissue data set 1 with the PBMC data set." (PMID 36304274, 2022). "The distribution of mRNA expression levels of STAMBPL1 and SNAI1 was analysed with split-violin plots, which shows the expression and the co-occurrence of STAMBPL1 (red) with SNAI1 (green) in each tumour type, including LUAD and BRCA." (PMID 32636467, 2020). "Importantly, we noticed that STAMBPL1 KD contributed to enhancing the sensitivity of sunitinib in these cell lines, while ectopic overexpression of STAMBPL1 increased sunitinib resistance of the tumor cells." (PMID 39527690, 2025). "Our results above demonstrated that inhibition of STAMBPL1 dramatically upregulated multiple immune response genes that might enhance anti‐tumor immunity." (PMID 39527690, 2025). "All these results hinted that the STAMBPL1 positively mediated tumor growth in vitro." (PMID 38419066, 2024). "Additionally, the suppression of STAMBPL1 inhibits tumor growth and the proliferation in colorectal and gastric cancer cells." (PMID 37511599, 2023). "This new mechanism may be useful to develop therapeutic strategies targeting STAMBPL1 in tumours that have high STAMBPL1 and Survivin protein levels." (PMID 35066747, 2022). "Notably, the tumor cell and peripheral blood mononuclear cells (PBMCs) coculture assay demonstrated that decreased STAMBPL1 expression could lead to enhanced CD8+ T cell–mediated cytotoxicity." (PMID 39527690, 2025). "Besides, upregulation of STAMBPL1 could significantly enhance the tumor growth rate and volume in nude mice." (PMID 38419066, 2024). "This algorithm found that STAMBPL1 expression level was negatively correlated in LUAD (r −0.22, p < 0.0001) and in BRCA (r −0.37, p < 0.0001) to the EMT scores, which further confirm STAMBPL1 to be significantly associated with mesenchymal traits in tumours biopsies, thus focused on in this study." (PMID 32636467, 2020). "Therefore, we investigated whether STAMBPL1 promotes tumor angiogenesis." (PMID 40208233, 2025). "Specifically, disruption of the STAMBPL1/AXL axis will provide therapeutic benefits by reducing mesenchymal phenotypes and enhancing tumor immunogenicity." (PMID 39527690, 2025). "Immunoblotting assay was performed to confirm the protein level of STAMBPL1, TRIM21 and AXL in excised orthotopic tumor." (PMID 39527690, 2025).
tumor (continued). "The clinical results of the study show that STAMBPL1 is significantly increased in tumor tissues of HCC patients, and its expression is closely related to tumor size and TNM staging." (PMID 40607251, 2025). "This revealed a significant positive correlation between STAMBPL1 and SNAI1 in both tumour types, with a p value <0.0001." (PMID 32636467, 2020). "To substantiate the link between STAMBPL1 and Snail, we probed their clinical relevance in LUAD and BRCA tumour samples retrieved from the TCGA data sets." (PMID 32636467, 2020). "Similarly, overexpression of STAMBPL1 wild‐type, but not the enzyme‐dead mutant significantly restored tumor metastasis inhibition by STAMBPL1 KD, indicating STAMBPL1 promoted tumor progression in a DUB activity‐dependent mechanism." (PMID 39527690, 2025).
infection (1 paper, 2022). The state of being infected such as from the introduction of a foreign agent such as serum, vaccine, antigenic substance or organism. "In addition, an increasing multiplicity of infection (MOI) decreased the STAMBPL1 protein level congruently." (PMID 35066747, 2022).
STAMBPL1 also shares sentences with these, for which no sentence is quoted: breast ductal carcinoma (1 paper); kidney cancer (1); lung adenocarcinoma (1); multiple myeloma (1); non-small cell lung carcinoma (1); pancreatic adenocarcinoma (1); stomach cancers (1).